MET (MET proto-oncogene, receptor tyrosine kinase)
Diseases named in the same sentence as MET in open-access papers (continued):
Sharing a sentence is not in itself a finding about the gene and the disease.
cancer (continued). "MET is a promising target in cancer therapy because its signaling axis is involved in several types of cancer." (PMID 34974522, 2022). "The European Organization for Research and Treatment of Cancer (EORTC) 90101 “CREATE” phase II trial evaluated the MET inhibitor crizotinib in ASPS patients, achieving only limited antitumor activity." (PMID 35628499, 2022). "Recently, a number of agents that target the HGF/c-MET pathway have been developed and evaluated in preclinical and clinical studies of various cancers." (PMID 36034555, 2022). "The concept of targeting MYC to confer responsiveness to MET inhibition is supported by previous studies showing that MYC blockage overcomes the resistance of other types of cancer cell lines to MET inhibitors." (PMID 36433941, 2022). "The MET receptor has thus emerged as a druggable target across several human cancers and agents targeting MET and HGF, including small molecules such as crizotinib, tivantinib, and cabozantinib, have shown therapeutic effects in different tumors." (PMID 35480115, 2022). "Since AMPKa is a well-known autophagy regulator and MET is reported to play an important role in cancer progression, we want to know if MET can regulate AMPKa." (PMID 35635086, 2022). "Targeting the HGF/MET pathway is a promising strategy because it is involved in different cancer types." (PMID 35626056, 2022). "In summary, we have identified THEMIS2 as a novel regulator of cancer stemness and chemoresistance through interfering with the association of PTP1B with p-MET to promote MET signaling in TNBC cells." (PMID 34974522, 2022). "Our findings suggest that the MAPK pathway represents a main effector of METΔex14-driven cancer, lending credence to the possibility of combined MET-MAPK inhibition to improve therapeutic outcomes." (PMID 35326531, 2022). "Thayaparan and his team have engineered T-cells to express HGF as a chimeric antigen receptor to target c-MET expressing cancer cells." (PMID 35081970, 2022). "β-Catenin dependent transcription takes place via c-MET in colon cancer cells, converting it into a cancer stem cell (CSC)." (PMID 35081970, 2022). "MET inhibitors are active in patients with advanced MET exon 14-altered cancers and this abnormality is observed in 3–4% of NSCLC patients." (PMID 35329956, 2022). "It has been previously shown in cancer that c-MET expression in neutrophils is regulated by TNFα-dependent NF-κB activation." (PMID 35041723, 2022). "One potential target is the MET protein, which can be present on the surface of cancer cells, orchestrating aggressive behavior." (PMID 35326642, 2022). "Research has shown that RTKs EGFR/MET are responsible for sorafenib resistance and they were highly phosphorylated in multiply carcinoma cells including the lungs, breasts, and pancreas." (PMID 35428350, 2022). "We found EGFR/MET were mainly expressed in HCC cells of carcinoma tissue, which differed from some RTKs for clinical targets expressed mainly in peritumor tissue such as the PDGFR family." (PMID 35428350, 2022). "While MET gene amplification and exon 14 skipping are quite rare - less than 4% of total cancers - MET activation due to transcriptional overexpression is rather common, especially among carcinomas." (PMID 36271379, 2022). "c-MET is a receptor tyrosine kinase that is commonly upregulated in a wide variety of carcinomas and is activated in response to paracrine hepatocyte growth factor signaling from the stroma." (PMID 36530465, 2022).
cancer (continued). "Considering the important role of MET in tumorigenesis and development and its limited progress in cancer treatment applications, the current development of ADCs targeting c-MET has been accelerated." (PMID 33816276, 2021). "Determination of a high MET RNA‐ISH/low c‐MET IHC protein subgroup was found to be associated with poor 5‐year cancer‐specific outcomes compared to patients with concordant MET RNA‐ISH and c‐MET IHC protein expression (HR 2.12 [95%CI: 1.27–3.68])." (PMID 34428346, 2021). "Kinases that were rarely mutated, including MET, PIK3CB, and PDGFRA/PDGFRB, were found to be substantially overexpressed at the protein level in the same cancer types." (PMID 34552204, 2021). "In CRC, as in many other cancers, overexpression of c-MET is correlated with poor prognosis and metastasis." (PMID 34572947, 2021). "Aberrant activation of c-MET can lead to both tumor growth and metastatic progression of cancer cells, making it an important drug target for cancer treatments." (PMID 34210960, 2021). "In this study we have investigated FAMC3 copy number gain in different cancers and its potential connection to MET amplifications." (PMID 33596971, 2021). "HGF, a scattering factor, influences cancer cell proliferation, survival, invasion, and metastasis through interaction with c-MET." (PMID 33466394, 2021). "We demonstrate in this MET-driven subset of EGFR TKI-refractory cancers that canonical EGFR downstream signaling was governed by MET, even in the presence of sustained mutant EGFR expression and activation." (PMID 34516823, 2021). "The key role of the receptor tyrosine kinase c-MET for cell survival and cancer progression in patients with HNSCC support c-MET as promising target for anticancer therapy." (PMID 33919702, 2021). "Correlations between expression of c‐MET and resistance to cisplatin and ionizing radiations in several types of cancer, or between NOTCH3 expression and enhanced cisplatin resistance, are good illustrations of their implications." (PMID 34542930, 2021). "We also observed that genetic alterations of c-MET/EGFR in CRC co-occurred with other gene alterations and were associated with overexpression of messenger (m)RNA of some cancer hallmark proteins." (PMID 34512327, 2021). "There are three tyrosine kinase inhibitors (TKIs) which target MET that are currently approved for use as monotherapy in the treatment of cancers - crizotinib (PF-02341066), cabozantinib (XL-184) and capmatinib (INC280)." (PMID 33526881, 2021). "Blocking of the HGF/MET axis by the Combo treatment was extremely specific, with untreated and Combo-treated cancer cells giving rise to a superimposable expression profile." (PMID 34298732, 2021). "Additional mechanisms of constitutive activation of MET signaling in cancer cells are MET gene fusions and MET-gene copy number gain/amplification (MET-GCNG/GA)." (PMID 34884673, 2021). "These two studies indicate that MET activation on endothelial cells by HGF secreted by cancer cells can facilitate chemoresistance in two different ways." (PMID 33526881, 2021). "The positive expression of MET was significantly correlated with cancer recurrence and metastasis (X2 = 4.726, p = 0.030)." (PMID 34123778, 2021). "Total ERBB3 expression in DFCI81 and DFCI161 cells increased after MET inhibition, a compensatory mechanism reported in other receptor tyrosine kinase–driven cancers treated with TKI." (PMID 34516823, 2021). "Our mechanistic experiments showed that miR-34a directly interacts with the proto-oncogene MET and attenuates the MET signaling axis by posttranscriptional gene regulation in cancer cells." (PMID 33596979, 2021). "This is in accordance with previous work showing that when targeted therapy is effective in EGFR-mutated cancer cell lines, EGFR is downregulated, and further supports the effectiveness of the crizotinib and osimertinib combination in EGFR/MET-driven tumors." (PMID 34298655, 2021).
cancer (continued). "Reported data indicate that cancer cells harboring FGFR1 amplifications can acquire resistance to FGFR inhibitors mediated by overexpression of NRAS, MET amplification, mutational inactivation of PETN, and activation of AKT." (PMID 34114373, 2021). "While MET overexpression and activation by HGF does not warrant its designation as a pivotal CSC marker, these studies demonstrate a role played by MET signaling that enhances therapeutic resistance and stem cell maintenance in these cancers." (PMID 34055785, 2021). "To evaluate the sensitivity of HNSCC cell lines, first we investigated the in vitro effects of EGFR, RAS and c-MET inhibitors on cancer cell proliferation." (PMID 34257586, 2021). "In the future, tivantinib or c-MET-targeted therapy in cancers, either monotherapy or combinations, needs further investigations." (PMID 34804015, 2021). "Growth factor HGF/SF binds and activates MET, normal activation induces embryogenesis, while abnormal activation of MET in cancer leads rapid progression by activating multiple signaling pathways including Ras, PI3K, STAT, Wnt, and Notch signaling pathway." (PMID 34262595, 2021). "NCI-H820 cancer cells express an EGFR drug-sensitive mutation (an exon 19 deletion), an EGFR drug-resistance mutation (T790M), activated AXL, and MET amplification, conferring resistance to erlotinib, gefitinib, and afatinib." (PMID 34203709, 2021). "The MET pathway is frequently dysregulated in cancer and acquired genomic aberrations can lead to treatment refractory disease with EGFR tyrosine kinase inhibitors." (PMID 34428346, 2021). "The treatment of the cancer cells with cabozantinib and compound 4 at the same concentration significantly reduced the expression of c-MET and its phosphorylation in a time-dependent manner, and such change by compound 4 was much greater than by cabozantinib." (PMID 34575841, 2021). "In conclusion, this work highlights a new role for TNC, representing a newly discovered link between MET-expressing cancer cells and the stroma compartment." (PMID 34298732, 2021). "For some RTK members, such as MET, specific proteolytic cleavage is a process that is closely related to cancer development." (PMID 33947097, 2021). "Among the RTKs, the HGF/MET axis frequently has been reported to be responsible for resistance to inhibition of other RTKs in various types of cancer and in GBM." (PMID 34806012, 2021). "Different mechanisms of MET activation have been described in human cancer including protein overexpression, gene amplification, point mutation, exon 14 deletion and paracrine or autocrine activation via HGF." (PMID 34200749, 2021). "By further exploiting the mechanisms of MET-mediated chemoresistance and optimising patient stratification, there is hope for improved outcomes in targeting MET in patients with chemotherapy resistant cancers." (PMID 33526881, 2021). "Depletion of AP-1 or GGA2 also reduced cell contents of other tyrosine kinases, MET and ErbB4, and therefore, suppressed the growth of H1975 cancer cells in culture and xenograft model." (PMID 34799560, 2021). "70% of patients had coamplifications of receptor tyrosine kinase or other cancer-promoting genes, including MET, KRAS, FGFR1, IGFR1, SRC and VEGFA18–20, potentially associated with resistance to EGFR-inhibitors." (PMID 33199443, 2021). "MET, one of the receptor tyrosine kinases, is related to embryogenesis, organofaction, tumourigenesis, and cancer metastasis." (PMID 34761497, 2021). "MET, otherwise known as Hepatocyte Growth Factor Receptor or c-MET, is known to be upregulated in several types of cancer and to protect from apoptosis." (PMID 34884451, 2021). "This highlights the importance of utilizing MET inhibitors to radio-sensitize tumors by reducing the malignant nature of the radio-resistant GSCs thereby increasing the possibility of long-term, cancer-free cures." (PMID 34055785, 2021).
cancer (continued). "Pathological MET activation has been suggested as a therapeutic target for cancer treatment since it promotes proliferation, invasion, migration, and tumor cell metastasis." (PMID 34217156, 2021). "It interacts with MET to activate a signaling pathway that promotes cancer growth, survival, and invasion." (PMID 34572947, 2021). "In NSCLC cancer cells resistant to EGFR or MET inhibition, a metabolic shift towards increased glycolysis and lactate production resulted in acidification of the TME." (PMID 33804114, 2021). "Proliferative activity is a vital component of cancer development and progression, with the MET/HGF axis being a known molecular regulator." (PMID 33526881, 2021). "Since an emerging role of precision and personalized medicine for cancer treatment, c-Met or MET serving as a biomarker for the management of cancer merits further exploration." (PMID 34804015, 2021). "A study reported that the inhibition of the c-MET signaling pathway is a potential treatment modality for various human cancers, including CRC." (PMID 34360807, 2021). "Because of the importance of c-MET in many cancer types, inhibitors of c-MET are in clinical trials as cancer treatment, but a significant percentage of tumors acquire resistance to these treatments." (PMID 33596971, 2021). "In this present study, we found 130 out of 218 TNBC patients (59.6%) was positive for MET in the cancer tissue which were significantly higher than that in adjacent tissues." (PMID 34123778, 2021). "Aberrant activation of c-MET can lead to both tumors growth and metastatic progression of cancer cells." (PMID 34210960, 2021). "A number of small-molecule MET inhibitors have recently been developed and are currently undergoing clinical trials to determine their efficacy in reducing cancer morbidity and mortality." (PMID 34857794, 2021). "The NEAT1–MET axis was identified as gain interaction in our pan-cancer core component, suggesting that the competitive relation between NEAT1 and MET happened in cancer environment." (PMID 34222227, 2021). "Our first challenge was to distinguish between HGF/c-MET-activated and -inactivated samples within the 11 different cancers." (PMID 34261467, 2021). "Overall, 34 specimens harbored driver mutations in five cancer genes (EGFR, PIK3CA, KRAS, CTNNB1, and MET), which are canonical driver mutations." (PMID 33407425, 2021). "ILEI knock-down and c-MET inhibition effects on proliferation and invasiveness of five cancer cell lines and growth of xenograft tumors in mice were then investigated." (PMID 33596971, 2021). "Mechanistically, they show that cancer cells treated with TKIs targeting MET and EGFR secrete higher levels of lactate, which then instructs CAFs to secrete HGF, resulting in the non-responsiveness of cancer cells to the treatment." (PMID 34298736, 2021). "To determine the frequency of CN amplification of the FAM3C and MET genes, we investigated a variety of datasets of different cancer entities from the TCGA database." (PMID 33596971, 2021). "Alterations in HGF and MET expression are commonly reported in different types of cancers such as non-small cell lung cancer (NSCLC), GI tumors, and hepatocellular cancer (HCC)." (PMID 34037097, 2021). "Nevertheless, activation of the MET kinase is relevant not only in cases of oncogene addiction: in fact, cancer cells exploit the MET-driven invasive growth program to arrange and sustain the adaptive response to adverse micro-environmental conditions." (PMID 33446252, 2021). "Extensively studied in cancer, FN is known to stimulate OC cell proliferation and support cell adhesion and migration via α5β1-integrin/c-MET/FAK/Src pathway." (PMID 34162871, 2021). "All specimens were from patients who had developed clinical resistance to EGFR inhibitor treatment and whose resistant cancers demonstrated MET amplification as defined by targeted NGS or FISH." (PMID 34516823, 2021).
cancer (continued). "In contrast, a large number of studies have shown that HGF/c-MET activation affects cancer prognosis, but we found a significant relationship only in a small number of cancers by comparing HGF/c-MET expression and survival prognosis in 11 cancer patients." (PMID 34261467, 2021). "CDK6 and MET showed higher alteration rates in proteomic level than the genomic level consistent across at least four cancer types." (PMID 34552204, 2021). "Investigation of the mechanisms involved showed interplay between the two separate ILEI and c-MET signaling pathways during cancer invasion, suggesting MET amplifications are in reality MET-FAM3C co-amplifications with tight functional co-operation." (PMID 33596971, 2021). "In preclinical and clinical trials, it has been demonstrated that c-MET inhibitors exhibit antitumor activity in the treatment of multiple types of cancers, especially in NSCLC." (PMID 34261467, 2021). "This system fullfills the requirement for MET activation in conditions of expedience, and allows to evaluate the contribution of the HGF/MET axis to the dissemination of human cancer cells." (PMID 33446252, 2021). "In line with this, the cBioPortal database OncoPrint analysis shows that most of these RTKs have the highest alteration rate, such as EGFR = 10%, ERBB2 = 7%, BRAF = 7%, ROS1 = 5%, and MET = 3%, in 165 (44,752 patients/46,632 samples) cancer cohort studies." (PMID 34769090, 2021). "The proto‐oncogene MET, which is highly expressed in CRPC, is known to be associated with cancer occurrence, progression, and treatment resistance." (PMID 34761497, 2021). "It has been shown that expression levels of MET are high in cancer tissues and in corresponding affected lymph nodes." (PMID 33996551, 2021). "Another previously investigated mechanism involves tumors overexpressing the tyrosine kinase receptor MET, which is a common feature in many cancer forms." (PMID 34069138, 2021). "US7767675B2 reveals imidazotriazines and imidazopyrimidines as MET inhibitors and their pharmaceutical compositions useful in cancer treatment." (PMID 34451807, 2021). "Both MET amplification and c‐Met overexpression have been associated with poor clinical outcomes, underscoring the importance of increased c‐Met signaling in some cancer types." (PMID 33675179, 2021). "EGFR and c-MET are co-expressed in multiple cancers including GBM, supporting the notion that their downstream signaling contributes toward this malignant phenotype." (PMID 34055785, 2021). "We found that 130 and 65 out of 218 TNBC patients were positive for MET in the cancer and adjacent tissues respectively." (PMID 34123778, 2021). "c-MET has been shown to be essential to maintain the subpopulation of cancer stem cells (CSCs) within tumors." (PMID 33919702, 2021). "MET activity regulates not only proliferation but also cancer cell motility, invasion, and eventual metastasis." (PMID 33898310, 2021). "In fact, MET is involved in cancer progression, and some tumors are driven by MET alterations, such as amplification and overexpression." (PMID 34925346, 2021). "Among L1 host genes potentially involved in cancer, MET oncogene is of particular interest as its aberrant activation contributes to tumor onset, progression and metastasis of different types of solid tumors, including carcinomas." (PMID 34372923, 2021). "Our in vitro data with the 3D model indicated that HGF + c-MET inhibition significantly reduces cancer cell stemness (as assessed by ALDH-1 expression)." (PMID 32203220, 2020). "Next, we used the TPRMET-NIH3T3 cell line to analyze the effects of the combined treatments of MET- and mTOR-targeted MET on MET-driven cancer cells." (PMID 32764535, 2020). "We, therefore, explored the effects of MRC5 on the PDAC cell lines AsPC-1 (metastatic origin, high MET expression) and MIA PaCa-2 (primary cancer origin, low MET expression), which were co-cultured as suspended spheroids in ultra-low attachment plates." (PMID 32485915, 2020).